KMO (kynurenine 3-monooxygenase)
Diseases named in the same sentence as KMO in open-access papers (continued):
Sharing a sentence is not in itself a finding about the gene and the disease.
cancer (40 papers, 2010 to 2025). A tumor composed of atypical neoplastic, often pleomorphic cells that invade other tissues. "This molecular characterization makes KMO a potential cancer biomarker for objectively describing the risk of clinical outcomes, such as for cancer recurrence or the reflection on therapeutic intervention." (PMID 34683090, 2021). "Because tumor malignancy determines the survival outcome of cancer patients, we next evaluated the association between KMO expression and the overall survival rate of dogs with CMTs." (PMID 31186637, 2019). "Indeed, modulation of KYNA production by KMO inhibition has gained interest in the past decades and is a promising therapeutic approach for disease states linked to neurodegeneration, major depression, cancer, and immunological abnormalities." (PMID 31781097, 2019). "Given that KMO is overexpressed in various cancer types and contributes to cancer progression, the creation of KMO inhibitors emerges as an innovative approach for cancer therapy." (PMID 41332472, 2025). "In fact, IDO, TDO, or KMO inhibitors were found effective as antineoplastic agents in certain types of cancer." (PMID 39337426, 2024). "KMO, a critical enzyme within the kynurenine pathway, facilitates the conversion of tryptophan to 3-HK and is intricately involved in immune regulation, cancer development, inflammation, and metabolism." (PMID 39026250, 2024). "Combination treatment with R0-61-8048, a potent competitive inhibitor of KMO, and anti-PD-L1 antibody yielded superior anti-cancer efficacy compared to either treatment alone." (PMID 37876966, 2023). "Collectively, these findings demonstrate a cancer cell intrinsic function of KMO that promotes tumor aggressiveness and pluripotency." (PMID 37876966, 2023). "Upregulation of KMO has been reported in several cancer types, including TNBC, CRC, HCC, and astrocytoma." (PMID 37876966, 2023). "was shown to block the kynurenine pathway by downregulating KMO mRNA, demonstrating implications for cancer immunotherapy." (PMID 36290320, 2022). "KAT I and KYNU are however up-regulated in 9 and 5 cancer types, respectively, but are co-expressed with KMO in only 1 or 2 cancer types." (PMID 36286592, 2022). "Knockdown of KMO decreased the expression of cancer stem cell markers, as well as the sphere-forming, migration, and invasion abilities of CRC cells." (PMID 33937026, 2021). "Wet-lab results can be used as evidence with the results from bioinformatics analyses, in which KMO is a malignant gene and a vital indicator for cancer prognosis." (PMID 34683090, 2021). "Although our finding suggests a possible link of KMO to cancer stemness, consolidative supporting evidence is required." (PMID 33937026, 2021). "Collectively, the current study suggests that KMO is a significant protein in the kynurenine pathway affecting cancer development." (PMID 34683090, 2021). "The role of KMO enzyme expression in cancer has rarely been studied in comparison to IDO and TDO2 enzymes." (PMID 34680327, 2021). "Though evidence related to the tumorigenic role of KMO has begun to be disclosed, comprehensive large-scale clinical analyses are needed to further demonstrate how KMO contributes to cancer development among co-expressed genes." (PMID 34683090, 2021). "Enzymes in the KP are indeed druggable, IDO inhibitors are in various stages of development to treat cancer, and KMO inhibitors have already been found to be effective in preclinical models of neuropathic pain." (PMID 32932826, 2020). "This indicated that the expression of KMO protein issignificantly associated with tumor malignancy and demonstrated the potential of KMO in discriminating malignant tumors from benign ones." (PMID 31186637, 2019).
cancer (continued). "Currently, the primary clinical treatments include inhibitors targeting different enzymes in the kynurenine pathway, such as IDO1 inhibitors, TDO inhibitors, and KMO inhibitors, which have shown efficacy in cancer, immune diseases, neurological diseases, and neurodegenerative diseases." (PMID 39940736, 2025). "KMO may play a role in promoting tumor proliferation, metastasis, and invasion, and knockdown of KMO enzyme can reduce cancer cell proliferation." (PMID 39132147, 2024). "Importantly, the overexpression of KMO led to the expression of various genes involved in the proliferation, survival, invasiveness, and metastasis of cancer cells." (PMID 36834531, 2023). "Although a limited number of studies focused on the biological activity of 3-hydroxykynurenine towards cancer cells, the involvement of KMO, the enzyme catalyzing the reaction of kynurenine conversion to 3-hydroxykynurenine, in carcinogenesis and cancer progression has been reported." (PMID 36834531, 2023). "As such, KMO may facilitate cancer progression and chemotherapy resistance via synergistically modulating inflammatory responses in tumors with a concomitant downregulation of detoxification pathways." (PMID 36360213, 2022). "KMO expression in various types of cancer, including BC, has been explored." (PMID 34683090, 2021). "Moreover, the molecular mechanisms of KMO involved in enabling cancer growth were also investigated." (PMID 34683090, 2021). "KMO expression in other types of cancer has also been explored." (PMID 34440798, 2021). "Indeed, some cancers such as HER2-positive and triple-negative mammary carcinomas overexpress the enzymes kynurenine 3-monooxygenase (KMO) and kynureninase (KYNU), causing increased production of anthranilic acid." (PMID 34517343, 2021). "The study also demonstrated that KMO knockdown in HCC cell lines by small interfering RNA (siRNA) transfection decreased cancer cell proliferation, thus suggesting that KMO could be a novel target for HCC treatment." (PMID 34680327, 2021). "Understanding the mechanisms of Kyn-induced apoptosis could reveal therapeutic opportunities, particularly in cancers where KP enzymes such as KMO are upregulated, and targeting Kyn accumulation might selectively induce apoptosis in tumor cells while not affecting normal tissues." (PMID 41350269, 2025). "Additionally, KMO is overexpressed in several diseases, especially in cancers like melanoma, colorectal cancer, and breast cancer, as well as in neurodegenerative diseases such as Alzheimer’s disease and Huntington’s disease, contributing to disease progression." (PMID 39940736, 2025). "Interestingly, using immunohistochemistry, flow cytometry, immunofluorescence assay, and transmission electron microscopy, Lai and colleagues demonstrated that KMO is highly expressed on the cell membranes of breast cancer tissues and the cancer cell surfaceome of cell lines." (PMID 37876966, 2023). "Moreover, the increase in plasma [Kyn] in patients with cancer can also result from an additional increase in the flux of plasma free Trp down the KP and also a potential inhibition (down-regulation) of KMO, as occurs in many cancer types: all being determinants of the [Kyn]/[Trp] ratio." (PMID 36286592, 2022). "KMO inhibition could be regarded as a double-edged sword in relation to cancer." (PMID 36286592, 2022). "While IDO inhibitors have already reached clinical trials, they are rather regarded as potential anti-cancer therapeutics; KMO inhibitors that could be of more interest as potential drugs in neurodegenerative diseases are still in the earlier pre-clinical stage of development." (PMID 33494373, 2021). "Moving forward, advancing research on KMO and TPH inhibitors in cancer therapy is essential, offering a fresh viewpoint on targeted Trp metabolism treatment for cancer." (PMID 41332472, 2025).
cancer (continued). "ASPNhigh/ KYNUhigh fibroblasts were detected in the tumor periphery, where few cancer cells reside, and many were also IDO‐1‐positive and KMO‐positive." (PMID 34379869, 2022). "Whereas KP enzymes preceding KMO, and also the 2 Trp transporters SLC1A5 and SLC7A5, are up-regulated in 32-46% of cancer types, KMO and subsequent enzymes show lesser expression, ranging from 3 to 18%." (PMID 36286592, 2022). "In accordance with this, KMO is the pivotal enzyme in the KP that leads to NAD+ synthesis and is related to poor prognosis in several cancers." (PMID 34440798, 2021). "In this study, we have further investigated cancer clinical databases—namely, the TCGA and GTEx databases—to verify that, in addition to TNBC, KMO and its correlated genes can be used as important indicators of prognosis in different types of human BC." (PMID 34683090, 2021). "Assessing the importance of KMO in GBM and other cancers represents a novel field for understanding tumor cell biology with promising results." (PMID 34440798, 2021). "Nevertheless, the majority of KMO inhibitors currently being studied are aimed at neurodegenerative conditions, with no reported clinical trials specifically for cancer treatment." (PMID 41332472, 2025). "Several pharmacological strategies are currently under investigation, including indoleamine 2,3-dioxygenase 1 (IDO1) inhibitors, kynurenine 3-monooxygenase (KMO) inhibitors, and tryptophan mimetics, primarily in the context of cancer, neurodegeneration, and chronic inflammatory diseases." (PMID 40426950, 2025). "Other abnormalities in KYN pathway activity in tissues of RCC patients include lower expression of QPRT and downregulation of KMO and 3-HAAO, although QPRT activity may vary in different types of cancers." (PMID 39337426, 2024). "Moreover, the link between tryptophan metabolism pathways and cancer has prompted a lot of researches on treatments targeting the kynurenine pathway, especially by inhibiting the key enzymes including TDO, IDO1 and KMO." (PMID 35494045, 2022). "Of interest, overexpression of KMO has been suggested to contribute to the malignant phenotype of TNBC cells, particularly cancer stem cell (CSC) properties, and 3) KMO-induced β-catenin stabilization, which also leads to increased expression of pluripotent genes such as Nanog, Oct4, and Sox2." (PMID 36077608, 2022). "Furthermore, the key genes correlated with KMO, such as the MYD88, IRF1, IL-18, and CASP1 genes, manipulate the inflammation where many cancers arise." (PMID 34683090, 2021). "Kynurenine‐3‐monooxygenase (KMO) is an enzyme that relies on nicotinamide adenine dinucleotide phosphate (NADP), a key site in the kynurenine pathway (KP), which has great effects on neurological diseases, cancer, and peripheral inflammation." (PMID 32148781, 2020). "Thus, we have demonstrated that the well-described role played by the KP in mediating cancer immune tolerance extends beyond IDO1, potentially identifying KMO and KYNU inhibitors as new therapeutic BrCa targets." (PMID 33109232, 2020). "Genetic modifications, including knockout animals, animals with KAT or KMO overexpression, may introduce significant changes in KYNA level in particular organs or the entire organism and may result in a better understanding of the role of KYNA in the cancer promotion and progression." (PMID 31659416, 2020).
tumor (33 papers, 2015 to 2026). "The molecular interplays between KMO and the co-expressed genes were also investigated here, and the results revealed that they cause tumor-promoting inflammation and thereby expedite tumor progression." (PMID 34683090, 2021). "The level of KMO expression was also significantly associated with tumor malignancy, tumor size, and tumor recurrence." (PMID 31186637, 2019). "Consequently, KMO is associated with various conditions, including cardiovascular diseases, neurological disorders, tumor formation, and inflammation." (PMID 39026250, 2024). "Notably, induction of KMO in immune cell subtypes has also been linked to dysfunctional anti-tumor activity." (PMID 37876966, 2023). "High IDO1 and KMO levels were linked to advanced-stage disease, while KAT and KYNU were associated with earlier stages and lower tumor grade." (PMID 42095396, 2026). "Key enzymes of the KYN pathway, including TDO2 and KMO, were upregulated in most early-stage tumours, consistent with previous transcriptomic and proteomic studies using IHC36,37." (PMID 40348885, 2025). "This seminal paper systematically assessed the therapeutic potential of key enzymes—IDO1, IDO2, TDO, and KMO (Kynurenine 3-monooxygenase)—highlighting their roles in immune modulation and tumor immune evasion." (PMID 40666095, 2025). "In the CRC cohort, enzymes of the KYN pathway, including TDO2 and KMO were upregulated in early-stage tumour tissues, consistent with previous studies." (PMID 40348885, 2025). "Modulating Trp metabolism by inhibiting KMO expression offers a potential avenue for impacting tumor growth and immune response." (PMID 38462620, 2024). "More information is needed to understand how KMO works in malignant cells as well as other types of cells that form a tumor mass." (PMID 34440798, 2021). "Pharmacological inhibition of KMO also seems to have great potential as the therapeutic target for the treatment of certain neoplasms, such as MM." (PMID 34201791, 2021). "In vitro pharmacological inhibition of KMO reduces tumor cell viability and STAT3 and pSTAT3 expression, confirming an oncogenic role of KMO outside of its catabolic activity." (PMID 34440798, 2021). "Nevertheless, immunostaining for KMO showed that the protein is mainly localized to GFAP+ cells, indicating that tumor cells of the astrocytic lineage express KMO, but also in a heterogeneous way between different tumor samples." (PMID 34440798, 2021). "The results showed that KMO expression in tumor tissues was significantly higher than that in normal tissues." (PMID 33937026, 2021). "Our previous studies have reported that the expression of KMO is positively correlated with tumor progression in canine tumors and human TNBC." (PMID 34683090, 2021). "Our results manifested that inhibition of KMO activity represses cell migration, invasion, and tumor sphere formation." (PMID 33937026, 2021). "Further studies investigating the effects of IDO1, TDO, or KMO inhibition on tumor immune response should also take the impact on neurobehavioral manifestations into consideration." (PMID 32153576, 2020). "Critically, one can expect that loss of KMO, alongside an increase in IDO expression, will lead to the accumulation in tumour tissue of kynurenine." (PMID 32390008, 2020). "Investigating compounds involved in selenium metabolism could elucidate the role of KMO in tumor immune escape and disease progression, potentially identifying it as a target for combinational therapy." (PMID 41170198, 2025). "Aberrant expression of KMO in tumors may significantly influence immune regulation within the tumor microenvironment." (PMID 41170198, 2025). "Numerous studies demonstrated that KMO played a key role in tumorigenesis and tumor progression." (PMID 36386216, 2022). "Therefore, elevated KMO shifts the pathway towards the formation of 3-HK and QA and regulates the immune response and tumor tolerance." (PMID 34683090, 2021).
tumor (continued). "The mRNA expression of KMO in various tumor samples was analyzed using the Oncomine database." (PMID 34683090, 2021). "Thus, the importance of KMO in GBM cells supports two of the main characteristics of the tumor microenvironment, namely metabolic activity and immune response modulation, making this enzyme a promising target for further study on GBM." (PMID 34440798, 2021). "KMO expression was higher in CRC tumor tissues than in healthy tissues and polyps." (PMID 33937026, 2021). "Collectively, these results indicated that the KMO may enable tumor progression together with its correlated genes by triggering inflammatory responses within tumors." (PMID 34683090, 2021). "The KMO protein expression was localized in GFAP+ cells in tumor tissue." (PMID 34440798, 2021). "Recently, it was reported that downregulation of KMO activity significantly inhibited cell proliferation of tumor cells and KMO may be a potential biomarker for tumor diagnosis (Chiu, Lei, Huang, Chiang, & Lin, 2019)." (PMID 32148781, 2020). "Taken together, the findings indicated that KMO is a potential biomarker for tumor diagnosis, and this might open up new perspectives for clinical applications of CMT." (PMID 31186637, 2019). "A high level of KMO promotes the synthesis of downstream metabolites of the kynurenine pathway, such as 3-HK, 3-hydroxyanthranilic acid, and quinolinic acid, which participate in the regulation of the immune response and tumor tolerance." (PMID 31186637, 2019). "Presently little is known about KMO for its significance on tumor development." (PMID 31186637, 2019). "Hence, KMO has the potential to serve as a biomarker for the prediction of tumor development or grading, and it could even be designed as a therapeutic agent for immunotherapy." (PMID 34683090, 2021). "Therefore, KMO and its co-expressed genes could synergistically facilitate tumor progression via enhancing chronic inflammation and triggering chemokines within the tumor microenvironment." (PMID 34683090, 2021). "The results showed that CCR7, KMO, IF57, and HDAC9 were highly expressed in HNSCC tumor tissues, while ZNF439 was highly expressed in normal tissues." (PMID 40145017, 2025). "The expression levels of COLEC10, KMO, and GNMT were observed to be markedly reduced in tumor tissues compared to matched normal counterparts (P < 0.05)." (PMID 40026364, 2025). "The expression patterns of COLEC10, KMO, and GNMT in LIHC were correlated with tumor staging (P(NF) < 0.05)." (PMID 40026364, 2025). "Analysis of the expression of the TILB-related signature genes in B Plasma cells showed that KMO, IFT57, HDAC9, GSAP, and CCR7 were significantly highly expressed in tumor tissue, while ZNF439 and KDM5D showed a similar trend." (PMID 40145017, 2025). "The results showed that ZNF439 and KDM5D were highly expressed in normal tissues, whereas KMO, FT57, HDAC9, GSAP, and CCR7 were highly expressed in tumor tissues." (PMID 40145017, 2025). "The results revealed that in comparison with the normal tissues, tumor tissues from ccRCC patients exhibited obviously high CYP1B1, KMO, and TDO2 staining." (PMID 38183155, 2024). "KMO expression is correlated with tumor differentiation, and patients with HCC with elevated KMO expression exhibit decreased overall survival and a higher risk of disease recurrence." (PMID 38462620, 2024). "The expression of CYP1B1, KMO, and TDO2 in tumor tissues was significantly upregulated in comparison with those in adjacent normal tissues." (PMID 38183155, 2024). "Our previous studies also proved that KMO is overexpressed in canine mammary tumours (CMT) and canine melanoma and plays an oncogenic role in tumour development." (PMID 34980125, 2022). "The next step was to quantify the KMO mRNA expression, KMO mRNA protein, and KMO activity in GBM tumor tissue." (PMID 34440798, 2021).